DVL1 (dishevelled segment polarity protein 1)
Description:
Participates in Wnt signaling by binding to the cytoplasmic C-terminus of frizzled family members and transducing the Wnt signal to down-stream effectors. Plays a role both in canonical and non-canonical Wnt signaling. Plays a role in the signal transduction pathways mediated by multiple Wnt genes. Required for LEF1 activation upon WNT1 and WNT3A signaling. DVL1 and PAK1 form a ternary complex with MUSK which is important for MUSK-dependent regulation of AChR clustering during the formation of the neuromuscular junction (NMJ).
Synonyms: DRS2; DVL; DVL1L1
Tractability: Small molecule: a structure with a bound ligand is known. Antibody: UniProt places it where antibodies can reach, with medium confidence; its Gene Ontology location is reachable by antibodies, with medium confidence; the Human Protein Atlas places it where antibodies can reach. PROTAC: UniProt records ubiquitination sites on it; ubiquitination databases record sites on it; its protein half-life has been measured; a small molecule that binds it is known.
Gene: Protein-coding gene on chromosome 1 (1,335,276 to 1,349,945, reverse strand). Ensembl gene ENSG00000107404.
Subcellular location: Cell membrane; Cytoplasm, cytosol; Cytoplasmic vesicle
Subcellular location (Human Protein Atlas): Nucleoplasm; Plasma membrane; Focal adhesion sites; Vesicles
Pathways (Reactome):
Signal Transduction: Degradation of DVL; Disassembly of the destruction complex and recruitment of AXIN to the membrane; Negative regulation of TCF-dependent signaling by DVL-interacting proteins; PCP/CE pathway; RHO GTPases Activate Formins; TCF dependent signaling in response to WNT; WNT mediated activation of DVL
Disease: WNT5:FZD7-mediated leishmania damping
Gene Ontology:
Molecular function: enzyme binding; frizzled binding; identical protein binding; protein binding; protein kinase binding; beta-catenin binding; small GTPase binding
Biological process: canonical Wnt signaling pathway; neural tube development; positive regulation of proteasomal ubiquitin-dependent protein catabolic process; positive regulation of transcription by RNA polymerase II; protein localization to nucleus; protein stabilization; regulation of DNA-templated transcription; regulation of protein localization; Wnt signaling pathway, planar cell polarity pathway; dendrite morphogenesis; heart looping; neuromuscular junction development; neurotransmitter secretion; non-canonical Wnt signaling pathway; outflow tract morphogenesis; positive regulation of neuron projection arborization; positive regulation of protein localization to presynapse; presynapse assembly; receptor clustering; synapse organization; dendritic spine morphogenesis; intracellular signal transduction; positive regulation of excitatory postsynaptic potential; postsynapse organization; regulation of postsynapse organization; and 2 more
Cellular component: cytoplasmic vesicle; growth cone; lateral plasma membrane; neuron projection; cytosol; synapse; axon; clathrin-coated vesicle; cytoplasm; dendrite; dendritic spine; glutamatergic synapse; microtubule; microtubule cytoskeleton; neuronal cell body; neuronal dense core vesicle; plasma membrane; postsynaptic density; presynapse; Schaffer collateral - CA1 synapse; Wnt signalosome
Genetic constraint (gnomAD): Loss-of-function variants: 50 observed, 60.5 expected, observed/expected ratio (o/e) 0.83, 90% interval 0.66 to 1.05. The synonymous counts are far from expectation, so gnomAD's model fits this gene poorly and the ratio says little. Missense variants: 1,197 observed, 977.43 expected, observed/expected ratio (o/e) 1.22, 90% interval 1.17 to 1.28. Synonymous variants: 608 observed, 405.11 expected, observed/expected ratio (o/e) 1.5, 90% interval 1.4 to 1.61.
Homologues: Orthologues: chimpanzee DVL1 (99% identical), macaque DVL1 (99% identical), dog DVL1 (96% identical), pig DVL1 (95% identical), rat Dvl1 (95% identical), mouse Dvl1 (95% identical), guinea pig DVL1 (94% identical), tropical clawed frog dvl1 (81% identical), zebrafish dvl1b (70% identical), zebrafish dvl1a (52% identical), Drosophila melanogaster dsh (41% identical), Caenorhabditis elegans dsh-1 (37% identical), and 3 more. Paralogues in human: DVL3 (67% identical), DVL2 (61% identical), DIXDC1 (15% identical).
Diseases named in the same sentence as DVL1 in open-access papers:
DVL1 is named in the same sentence as 119 diseases in open-access papers, as found by Europe PMC text mining. Sharing a sentence is not in itself a finding about the gene and the disease. The quoted sentences say what the papers report.
breast carcinoma (24 papers, 2007 to 2025). "Wnt signaling is important for numerous cellular processes, and because DVL has been linked with migration in breast cancer cells, we examined the influence of lysine point mutants on DVL-1 in regulating cell migration." (PMID 34733415, 2021). "Herein, we extensively investigate association between DVL-1 expression with breast cancer subtypes, clinicopathological parameters, and various risk factors associated with breast cancer." (PMID 34659647, 2021). "DVL-1 is also linked with tumorigenesis, however its association with specific breast cancer (BC) subtypes and how it contributes to tumorigenicity remains poorly studied." (PMID 34659647, 2021). "Collectively, our study demonstrates that high levels of DVL-1 is observed in breast cancer versus healthy tissue and is markedly associated with poor prognosis in triple-negative breast cancer." (PMID 34659647, 2021). "Since the expression of both DVL-1 transcript and protein was significantly higher in breast tumor tissues, we next evaluated its association with different clinical parameters in breast cancer patients." (PMID 34659647, 2021). "DVL1 was also reported to be associated with distant metastasis and overall survival in breast cancer patients." (PMID 34288405, 2021). "In the context of human breast cancer, both epidemiological and functional data have implicated Wnt5a as a tumor suppressor and our data indicating that Wnt5a signals through DVL1 to inhibit rRNA synthesis provide a novel mechanism underlying that role." (PMID 27500936, 2016). "Here, we demonstrate that Wnt5a represses rRNA synthesis in breast cancer cells by promoting nucleolar localization of DVL1 and its subsequent association with rDNA chromatin." (PMID 27500936, 2016). "Moreover, we found DVL-1 to be significantly associated with various clinical risk factors for breast cancer patients such as cancer stage, menopausal status, ER, PR, HER2 receptor and triple-negative status." (PMID 34659647, 2021). "Importantly, we found that the immunosuppressive cytokine, IL-10 was positively associated with DVL-1 mRNA expression in breast cancer patients." (PMID 34659647, 2021). "Moreover, we found a correlation between DVL-1 and several risk-factors for breast cancer using UALCAN and bc-Gen ExMiner databases." (PMID 34659647, 2021). "As for DVL‐1, which is highly expressed in various tumor types including breast cancer, it is targeted for suppression in cancer therapies because it regulates oncogenic Wnt signaling, an important driver of tumor progression." (PMID 40576246, 2025). "In previous studies, we not only demonstrated that DVL translocates to the nucleus across multiple breast cancer cell lines but also that DVL-1 binds to multiple aromatase tissue-specific promoters and regulates their transcription." (PMID 34659647, 2021). "Altogether, we found that DVL-1 localizes at various transcriptional regulatory regions in breast cancer." (PMID 34659647, 2021). "To further assess the levels of DVL-1 protein expression in primary breast cancers, we performed immunofluorescence staining on resected tumors from patients with known molecular subtypes." (PMID 34733415, 2021). "Using ChIP sequencing analysis, we have identified that DVL-1 localizes at over 8000 genomic loci in breast cancer models." (PMID 34659647, 2021). "We found that expression of DVL-1 was significantly correlated with immune cell genes in different breast cancer subtypes (Luminal, n = 611; HER2-positive, n = 67; and TNBC, n = 139)." (PMID 34659647, 2021). "Downregulated miR-1247-5p associated with poor prognosis and facilitates tumor cell growth via DVL1 in breast cancer." (PMID 34456184, 2021). "This study utilizes publicly available data, bioinformatics tools, and genomic analyses to emphasize the contribution of DVL-1 in the most aggressive subtype of breast cancer known as triple-negative breast cancer." (PMID 34659647, 2021).
breast carcinoma (continued). "Next, the analysis based on different subtypes of breast cancer showed that expression of DVL-1 was significantly higher in luminal group (n = 566, p < 10−12) and triple-negative group (n = 116, p < 10−11) compared to normal control group." (PMID 34659647, 2021). "We start with examining the expression levels of DVL-1 in breast cancer using bioinformatics analysis which indicates high DVL-1 expression in breast cancer compared to non-cancer breast tissues, specifically in luminal B and triple-negative tumors." (PMID 34659647, 2021). "As shown in three independent experiments in a panel of breast cancer cell lines, we found that both DVL-1 and DVL-3 bind the I.1 promoter in MCF7, MDA-MB-231 and BT-549 while only DVL-3 binds to I.1 in MDA-MB-468." (PMID 30479694, 2018). "Wnt5a-induced accumulation of DVL1 in the nucleolus directly interferes with the synthesis of rRNA, suggesting that a tumor suppressive effect of Wnt5a in breast cancer cells is mediated by DVL1-dependent repression of rRNA synthesis." (PMID 27500936, 2016). "Amplification and increased expression of the DVL1 gene may have implications in human breast cancer through disruption of the Wnt signaling pathway." (PMID 36035311, 2022). "Here, we shed light on an important, yet unexplored aspect of DVL-1 expression and its association with the presence or absence of immune cell levels in breast cancer." (PMID 34659647, 2021). "Interestingly, our observations regarding nuclear DVL-1 are similar to one of the previously published studies where nuclear DVL-1 exerts tumor suppressive effects by inhibiting transcription of ribosomal DNA in breast cancer model." (PMID 34733415, 2021). "Interestingly, expression of some immune cell genes and DVL-1 uniquely correlated with luminal breast cancer, such as CD19, CD79A, CD8B, CCR7, CD1C, and STAT5B." (PMID 34659647, 2021). "Another study provided evidence that Wnt5a represses ribosomal RNA (rRNA) synthesis by promoting DVL-1 accumulation in nucleolus of breast cancer cells, where nucleolar DVL-1 releases Pol I transcription activator and SIRT7 from rDNA loci, thereby inhibiting tumor growth." (PMID 33126517, 2020). "Sulindac is a non-steroidal anti-inflammatory drug (NSAID) which also inhibits Wnt signaling by binding the PDZ domain of disheveled (DVL1) and like other NSAIDS, inhibits cyclooxygenase-2 (COX2), a gene recently implicated in breast cancer metastasis to the brain." (PMID 24209998, 2013). "By immunohistochemistry, Dvl1 was shown to be expressed in 50% of human breast cancers." (PMID 22655072, 2012). "Whether Dvl1 and Dvl3, homologs of Dvl2, induce the migration of breast cancer cells needs to be further studied." (PMID 22655072, 2012). "While several studies suggest that DVL proteins could serve as a potential prognostic biomarker for breast cancer and other cancer types, the true potential of DVL-1 and its contribution to clinical factors which regulate breast tumor progression and tumor immunology remained unanswered." (PMID 34659647, 2021). "Finally, we report that conserved DVL-1 lysines modulate various oncogenic functions such as cell migration, proliferation, cell-cycle progression, 3D-spheroid formation and in-vivo tumor growth in breast cancer models." (PMID 34733415, 2021). "Taken together, these results suggest that there may be an important link between DVL-1 expression in breast cancer cells and the suppression of T cell mediated anti-tumor responses, perhaps by transcriptionally repressing the expression of various immune cell-related genes." (PMID 34659647, 2021). "Further investigation demonstrates a differential role of nuclear DVL1 and DVL3 in regulating tissue-specific aromatase promoters and DVL1 binding to FZD7 promoters in breast cancer models." (PMID 33126517, 2020).
breast carcinoma (continued). "Herein, we demonstrate that DVL-1 proteins are over-expressed in TNBC cells compared to normal tissue lysates (NT) and hormone-receptor (ER/PR+) positive breast cancer cell lines." (PMID 31700102, 2019). "In SKBR3 cells, fructose-adaption increased expression of dishevelled homologue 1 (DVL1), a WNT target gene known to be dysregulated in breast cancers." (PMID 29796188, 2018). "The expression of AXIN, DVL1, and TCF4 showed variable levels in different TN breast cancer cell lines." (PMID 24143235, 2013). "DVL1 and DVL3 were consistently expressed at relatively uniform levels in all the breast cancer cell lines, whereas DVL2 was expressed in a more differential manner." (PMID 17897439, 2007). "Using TCGA breast cancer data cohort from UALCAN analysis platform, we confirmed that the expression of DVL-1 in breast cancer samples (n = 1097) was significantly higher than that in non-cancer/normal cancer tissues (n = 114) with a p-value <10−12." (PMID 34659647, 2021). "Amplification of DVL-1 was observed in 13 of 24 primary breast cancer patients in comparision to corresponding non-cancerous breast tissues, with a significant association in nuclear localization of DVL and β-catenin proteins." (PMID 34659647, 2021). "Moreover, previously we had shown that DVL-1 forms a complex with c-Jun and enriches at FZD7 promoter in breast cancer cells." (PMID 34733415, 2021). "The levels of DVL-1 antibody staining in three cases of breast cancer were high compared to the non-cancer adjacent tissues." (PMID 34659647, 2021). "Here we observed that, unlike K69 and K285, the K34 residue does not regulate cytosolic/nuclear DVL-1 ratios in breast cancer or HEK293 cells." (PMID 34733415, 2021). "DVL1 localized to CYP19A1 and regulated aromatase mRNA in breast cancer cells." (PMID 34456184, 2021). "By performing real time quantitative polymerase chain reaction (qRT-PCR) across a panel of breast cancer cell lines and a non-cancer line using intron-spanning primers, we determined the mRNA expression of DVL-1." (PMID 31700102, 2019). "We found that levels of DVL-1 proteins were relatively higher in triple-negative cells like MDA-MB-231, MDA-MB-468 and BT-549 cells compared to normal tissue lysates (NT) and hormone-receptor (ER/PR+) positive breast cancer cell lines." (PMID 31700102, 2019). "Interestingly, DVL-1 and DVL-3 were present at different levels in both nuclear and cytoplasmic fractions in multiple breast cancer lines." (PMID 30479694, 2018). "Given our previous findings demonstrating that DVL-1 plays a critical role in regulating a TIAM1-Rac1 signaling axis in MDA-MB-231 cells, and endogenous DVL-3 co-precipitates with SIRT1 in breast cancer cells, we were interested in exploring these two family members in particular." (PMID 30479694, 2018). "Moreover, DVL-1 was expressed at high levels in SW480 and SW620 colorectal cancer cell lines, but only at trace levels in MCF-7 and MDA-MB-231 breast cancer cells." (PMID 27779255, 2016). "Moreover, Dishevelled 1 (DVL1), a central regulator of Wnt signaling is found to be upregulated in breast cancer." (PMID 25499975, 2014). "Given that nucleolar size and elevated levels of rRNA synthesis correlate with poor prognosis in breast cancer, we posit that non-canonical signaling of Wnt5a through DVL1 and the consequent reduction in rRNA synthesis contributes to the role of Wnt5a in tumor suppression." (PMID 27500936, 2016). "Evidence that DVL1 can be specifically localized to the nucleolus was further shown by ectopic expression of FLAG-tagged DVL1 in fibroblasts lacking endogenous DVL1 protein as well as by immuno-electron microscopy of MCF7 cells stably expressing Wnt5a, and of MDA-MB-231 breast cancer cells." (PMID 27500936, 2016).
breast carcinoma (continued). "DVL-1 expression appears to negatively correlate with the presence of immune cells within the tumor microenvironment suggesting that DVL-1 could serve as suitable immune-modulating, prognostic biomarker for triple-negative breast cancer, a breast cancer type with unmet therapeutic needs." (PMID 34659647, 2021). "Based on the comprehensive ChIP Seq studies that we performed for DVL-1 and DVL-3 in breast cancer cell lines, we observed that DVL proteins target non-canonical genes." (PMID 34659647, 2021). "Extending analyses to other non-sirtuin deacetylases, we found that DVL-1 co-precipitates with HDAC1, a class I histone lysine deacetylase (HDAC), which is over-expressed in breast cancer cells." (PMID 31700102, 2019).